Y_RNA (Y RNA )
Gene: Miscellaneous RNA gene on chromosome 6 (31,402,152 to 31,402,250, reverse strand). Ensembl gene ENSG00000199332.
Homologues: Orthologues: macaque Y_RNA (95% identical). Paralogues in human: Y_RNA (97% identical), Y_RNA (94% identical), RNY3 (93% identical), Y_RNA (93% identical), RNY3P1 (92% identical), Y_RNA (91% identical), Y_RNA (90% identical), RNY3P11 (89% identical), Y_RNA (89% identical), RNY3P14 (88% identical), Y_RNA (88% identical), Y_RNA (87% identical), and 99 more.